SOX2 (SRY-box transcription factor 2)
Diseases named in the same sentence as SOX2 in open-access papers (continued):
Sharing a sentence is not in itself a finding about the gene and the disease.
tumor (continued). "Next, we tested the effect of SOX2 silencing on OSCC cell anchorage-independent growth by performing 3D tumor spheroid assay." (PMID 38096163, 2023). "Each cluster was identified as GBM tumor cells or macrophages based on the expression of SOX2 and CD68, respectively (Fig EV1B and C)." (PMID 37791581, 2023). "Characterization of SOX2 expression in surgically resected brain tissues from GBM patients was next accomplished in the tumor, peritumoral, and adjacent normal-appearing regions that were defined by histopathology (Fig 7D1–7D3)." (PMID 37058447, 2023). "We observed varying degrees of decrease in the fluorescence intensity of Oct4, Sox2, Aldh1a1, Epcam, and Itgb1 in tumor tissues formed by 66cl4-shSix1 KD1-luc and 66cl4-shSix1 KD2-luc compared to those formed by 66cl4-SCR-luc." (PMID 38031089, 2023). "Compared with its expression in 10 normal tissues, SOX2 was significantly upregulated in N2‐3 stage NPC tumour tissues." (PMID 37658588, 2023). "SOX2 knockdown, on the other hand, often results in diminished levels of cell replication, invasion and treatment resistance in these tumor types." (PMID 37738673, 2023). "METTL14 is highly expressed in distinct tumor types and boosts stemness by enhancing SOX2 mRNA stability upon m6A modification." (PMID 37142269, 2023). "The expression of Sox2 has been previously found to be correlated with Ki67 index, larger tumours, and higher grade in IDC." (PMID 37553320, 2023). "In comparing the tumor core and edge regions, we found statistically significant elevations in proliferative marker Ki-67 as well as glial progenitor markers SOX2, Olig2, and NG2, (p < 0.05)." (PMID 37752585, 2023). "Treatment with DZ-CIS resulted in a significant decrease in SOX2 expression within tumor tissue, suggesting its effect on cells exhibiting stem cell or stem cell-like properties." (PMID 37268911, 2023). "Mechanistically, our data revealed that the DMRTA1 and SOX2 positive feedback loop promotes tumor progression as well as chemotherapy resistance in ESCC." (PMID 37744275, 2023). "Significantly increased SOX2 expression was observed in high malignant tumor tissue compared with low malignant tissues." (PMID 37809806, 2023). "CSCs, a subpopulation of cells, are characterized by some key markers, such as CD133, CD166, CD44, CD24, SOX2, OCT4, and ALDH, which are associated with tumor initiation, growth, and therapy resistance." (PMID 36827121, 2023). "Accumulating evidence has shown amplification of SOX2 gene locus and overexpression of SOX2 that in turn motivates cancer progression, including tumor initiation, EMT, metastasis, recurrence, CSLCs phenotype transformation and drug resistance." (PMID 37147666, 2023). "Subsequently, we found that active Notch signaling and downregulation of Sox2 are necessary for Kras-induced tumor formation." (PMID 37882674, 2023). "To address this question, we first used the MGH7 LUSC cell line, which was established in our laboratory and expresses high levels of TP63 and SOX2, and recapitulates the squamous histology of the patient tumor when injected into immunocompromised mice." (PMID 36305267, 2023). "SOX2 is necessary during organ development and the maintenance of stemness while also participating in tumor initiation, proliferation, migration, invasion, metastasis, resistance to therapy, and maintenance of stemness in malignant cells." (PMID 37891174, 2023). "The genetic knockout of Wls in hair follicle Keratin 15+ cells results in reduced tumor growth, incidence, and reduced SOX2-positive CSC cell numbers in the skin." (PMID 37686421, 2023). "Among these, SOX2 appears also upregulated in the tumor close margin vs healthy mucosa and this significantly correlates with tumor size and lymph node compromise." (PMID 38096163, 2023). "Dysregulation of SOX2 expression and activity occurs in several cancer types and often correlates with advanced tumor stages, unfavorable prognosis, and drug resistance." (PMID 38096163, 2023).
tumor (continued). "A survey of the literature indicates that SOX2 affects tumor progression by acting on several signaling pathways in a context-dependent manner." (PMID 38096163, 2023). "BCa cancer cells’ survival and spheroid-forming capability enhancement were induced by AKT phosphorylation due to IGF2/IGF1R induction, which was thought to be involved in molecular mechanism of SOX2 expression leading to poor tumor prognosis." (PMID 37196048, 2023). "It was showed that FN promoted tumor cell proliferation through activation of the PI3K/AKT/SOX2 signaling pathway in NSCLC." (PMID 37809806, 2023). "Based on the critical role of SOX2 in cancer stem cell maintenance and cancer progression, it has become an effective therapeutic target, and SOX2 peptide immunization has been shown to delay tumor onset and activate cytotoxic T lymphocytes in mouse models." (PMID 37063420, 2023). "SOX2 expression significantly decreased in the subcutaneous tumours of the SUCLG2‐AS1 knockdown group." (PMID 37658588, 2023). "Conversely, knocking down KLF4 resulted in an increase in Ki67, PITX1, and SOX2 expression levels, and an increase in the malignancy of tumor tissue." (PMID 37841446, 2023). "Our tumor profiling results underline the importance of customizing treatment to tumors that exhibit the highest combined expression of NR5A2 and SOX2, thereby maximizing the response to therapy." (PMID 38012687, 2023). "Mechanistically, it was identified that FN facilitated the activation of the integrin αvβ3/PI3K/AKT signaling pathway, which subsequently upregulated tumor stemness through the downstream transcription factor SOX2." (PMID 37809806, 2023). "In this same model, however, CAFs acted to restrain the dysplasia seen in tumor cells that expressed high levels of the oncogenic transcription factor SOX2, indicating a multifaceted role of CAFs in tumor progression." (PMID 37091337, 2023). "In triple‐negative breast cancer (TNBC), the autocrine loop formed by the VEGF/VEGFR2 axis involving STAT3, Myc, and Sox2 contributes to the enhancement of the tumor stem cell‐like phenotype." (PMID 38077251, 2023). "SOX2 expression is correlated with smaller size, and early tumor stage, and longer disease-free survival rate in OSCCs." (PMID 37859926, 2023). "METTL3 is highly expressed in distinct tumor types and boosts stemness by enhancing SOX2 mRNA stability upon m6A modification." (PMID 37149646, 2023). "Higher expressions of EPCAM, β-catenin, β-catenin (in the nucleus), c-Myc, and SOX2 were observed in the EPCAMhigh cells derived xenografted tumor tissues than in the EPCAMlow cell-derived xenografted tumor tissues (p < 0.05)." (PMID 36674577, 2023). "SOX2 is an important biomarker with respect to squamous cell dysplasia/ carcinoma staging and progression, tumor invasiveness and patient prognosis in SCC’s29,39,40." (PMID 37543673, 2023). "In this study, we show that lncRNA WAC-AS1 functions as a tumor promoter in OS by maintaining stemness through inducing SOX2 expression by serving as a ceRNA for miR-5047." (PMID 37957698, 2023). "Based on these initial studies, a series of additional cell markers, including Nestin and SOX2, that show differences in tumor initiation and self-renewal have been validated." (PMID 36805592, 2023). "The re-expression or abnormal dysregulated expression level of stemness genes, like oct4, sox2, klf4 and klf5, in differentiated cells are a common feature of the tumorigenesis process and have been well documented in many tumor types." (PMID 38137514, 2023).
tumor (continued). "We performed immunohistochemical (IHC) analysis within tumor heterotransplants derived from UROtsa As_I cells to get a better understanding of protein localization in vivo for SOX2, IVL, and GRHL1." (PMID 37298099, 2023). "Their epigenetic silencing (H3K9me3 labelling) inhibited EWS-FLI1 binding to the SOX2 enhancer (SRY-box transcription factor 2), thereby reducing its expression and altering tumor growth in vivo." (PMID 37752913, 2023). "Accordingly, either SOX2 depletion or inhibition of glycolysis by 2-DG led to a significant decrease in the tumor volume, tumor weight, uptake of 18F-FDG and SUVmax of xenografts, as well as VM formation in vivo." (PMID 38044399, 2023). "To further investigate the potential clinical value, we examined the SOX2 expression levels in tumor tissues of NSCLC patients by immunofluorescence staining." (PMID 37809806, 2023). "Having established the antagonistic role of Notch and Sox2 signaling on Kras-mediated development of the tumor-initiating type I/type II cells marker population, we investigated their effect on in vitro colony formation." (PMID 37882674, 2023). "Expression of Sox2 was detected at the tumor-dermal interface of primary murine and human cSCC specimens." (PMID 35892887, 2022). "Studies described in this report, together with our previous work, demonstrate that elevating SOX2 above endogenous levels leads to growth inhibition in multiple tumor cell lines representing different tumor types." (PMID 35454854, 2022). "Overall, it appears that while Sox2+ cells can act as slowly dividing stem cells, their primary action is as a tumour suppressor in the stomach by preventing Wnt/B-catenin signalling." (PMID 35269931, 2022). "Several publications report the high expression of SOX2 gene in different tumours, thus supporting its oncogenic role." (PMID 35820816, 2022). "In most cases, undifferentiated tumor cells express associated embryonic markers such as the OCT4, NANOG, SOX2, and CARM1 genes." (PMID 35274101, 2022). "Results indicated that the positivity of SOX2, Ki67 and Oct4 was reduced in tumor tissues with silenced LINC01806." (PMID 35599309, 2022). "Additional CSC markers Sox2, CD44v6, and Aldh1/2 expression were analysed after magnetically induced permanent tumor growth pressure in vivo in Apc;Lgr5-EGFP mice." (PMID 35177769, 2022). "In this regard, we evaluated the expression of SOX2 in blood mononuclear cells expressing tumor markers such as AXL, EGF, CD87, CD90, or CD276." (PMID 36142766, 2022). "Together, these studies strongly suggest that slow cycling/infrequently proliferating tumor cells hijack the growth restricting effects of elevated SOX2 operative during development resulting in chemotherapy resistance." (PMID 35454854, 2022). "have found that CD70 ablation in primary GBM cell lines can reduce the expressions of CD44 and SOX2 genes, inhibiting the tumor migration, growth, and ability to attract monocyte-derived M2 macrophages in vitro." (PMID 36275720, 2022). "Like many other developmental genes, SOX2 is abnormally expressed in a variety of human cancers and is involved in tumor progression and chemoresistance." (PMID 35309116, 2022). "The expression of CD133 is regulated by Sox2 and agents targeting or interfering with this transcription factor can reduce tumor-initiating ability, resistance to chemotherapy, and recurrence." (PMID 35311140, 2022). "We confirmed the restriction of SOX2 expression to tumor cells, PTPRC/CD45 to immune cells, SPI1/PU.1, CD68, and CD163 to ‘macrophages’, CD3G to ‘T cells’, and OLIG1/2 and MBP to oligodendrocytes." (PMID 35973991, 2022). "The immunohistochemistry results demonstrated that the positive expression of Ki67, NANOG, OCT4, and SOX2 was increased in the tumor tissues of mice following ALKBH5 overexpression, the effect of which was reversed by the silencing of UBE2C." (PMID 36551544, 2022).
tumor (continued). "Overall two facts were obtained from this study; first, there is a positive correlation between HH signaling and maintaining YAP protein stability and function in SOX2 expression as well as tumor growth." (PMID 35501851, 2022). "The expression of the stem cell markers Nanog, Oct4, and Sox2 in tumor tissues and tumor spheroids were also markedly downregulated by FKA treatment." (PMID 35912174, 2022). "Although Sox2 is essential during mammalian embryogenesis it is also known factor playing a dramatic role in tumor growth and drug resistance." (PMID 35207587, 2022). "Immunohistochemical staining showed that the expression of CD133 and SOX‐2 in U251 tumor tissue transfected with RIP2 plasmid was significantly up‐regulated." (PMID 36184801, 2022). "FOXO3, a transcription factor that can inhibit the transcription of SOX2, has tumor-suppressive functions in CSCs." (PMID 34795388, 2022). "It is generally well-known that SOX2 is a critical tumor stem cell marker and maintains stem cell like phenotype." (PMID 35365622, 2022). "SRY-box 2 (SOX2) expression is elevated in BCC tumour samples, and its knockdown inhibits migration and invasion of BCC cells in vitro." (PMID 35583632, 2022). "The findings presented here uncover a novel SOX2:MYC signaling axis that regulates tumor cell proliferation and demonstrate that SOX2 elevation decreases the expression of MYC and downregulates MYC target genes." (PMID 35454854, 2022). "SOX2 silencing augmented CD8+ T cells in tumours, and CD8+ T cells declined in part after the addition of cGAS inhibitor RU.521." (PMID 35415876, 2022). "SOX2 expression is essential for the maintenance of tumor-initiating cells, which display cancer stem cell-like characteristics." (PMID 35737114, 2022). "In pancreatic cancer, cooperation of Hh and EGFR signaling induced high-level expression of SOX2 that promoted both tumor initiation and tumor growth." (PMID 36118530, 2022). "The functional role of PI3K/AKT/mTOR signaling pathway in tumor progression and resistance to chemotherapeutic agents and the interconnectivity between SOX2 and PI3K/AKT have been previously proposed." (PMID 35309116, 2022). "Here, we employed a counterintuitive approach of overexpressing Yamanaka factors (Oct4, c-Myc, Sox2, and Klf4) and examined a conditioned medium (CM)-based treatment option with induced tumor-suppressing cells (iTSCs)." (PMID 35547745, 2022). "SOX2 staining was heterogeneous with a minority of positive tumor cells, a pattern consistent with its roles in a distinct subpopulation of cells such as ‘stem-like’ cells." (PMID 35737114, 2022). "SOX2 expression was significantly greater at the tumor rim than the core for both MDA231Br-GFP and U87MG models (matched Wilcoxon test, P < 0.001 and P < 0.01, respectively)." (PMID 35312755, 2022). "Characterization of the disseminated cells demonstrated that the cells expressed elevated levels of SOX2 compared with the parental cell population and were enriched for tumor-initiating cells." (PMID 35454854, 2022). "SOX9 is known to work downstream of SOX2 to control the luminal progenitor cell content resulting in increased tumor initiation, drug resistance, and poor prognosis." (PMID 35906698, 2022). "As an alternative method for G2 phase analysis and to avoid tissue disaggregation, levels of the G2 specific protein CENPF were determined with Sox2 co-staining to identify tumor cells." (PMID 36482431, 2022). "RT-qPCR analysis of the same i-SOX2 tumor cell lines demonstrated that MYC mRNA levels were significantly downregulated when SOX2 was elevated." (PMID 35454854, 2022). "The Zhao et al19 study also showed that miR-126 induced apoptosis by targeting the Sox2 gene, exerting its anti-tumor activity." (PMID 35943150, 2022). "It is worth noting that the expression of YBX1 and SOX2 in tissues adjacent to tumor area is significantly higher than that in normal tissues." (PMID 36397101, 2022).
tumor (continued). "PCAT1 deficiency inhibited NSCLC growth and tumorigenicity in vivo, and SOX2 overexpression dampened IR‐induced adaptive immune responses and promoted tumour growth." (PMID 35415876, 2022). "It was detected through qRT-PCR that miR-144-3p was notably overexpressed in tumor tissues compared with that in normal tissues while SOX2 expression was restrained in BC tissues." (PMID 35551606, 2022). "At the same time, the expression of tumour stem cell related factors (SOX2, OCT4 and Nanog) was suppressed in the existence of caudatin." (PMID 35387566, 2022). "We demonstrated that the pro-tumor effects and the activation of SOX2 was dependent on a TRIB3 manner, and the patient prognosis was influence by the TRIB3 expression." (PMID 35473511, 2022). "In particular, Oct4 and Sox2 are sufficient to induce stem cell properties and in vivo tumor-propagating potential in differentiated and non-tumor-propagating GBM cells." (PMID 36212415, 2022). "They found that it significantly suppresses the growth of the tumor with high SOX2 levels and inhibits the expression of markers involved in tumor growth, metastasis, and chemoresistance." (PMID 35267473, 2022). "Single-cell analysis of MB tumours following vismodegib treatment revealed an increase in the population of MBSCs, which express the oncogene, SOX2." (PMID 36230692, 2022). "Our finding that elevated SOX2 restricts the proliferation of tumor cells is also consistent with the reports of high SOX2 expression in infrequently proliferating tumor cells." (PMID 35454854, 2022). "Some double-negative feedback loops, including miR-143 (LIMK1, SOX2) and miR-145 (ADAM17, NEDD9, SOX2), also result in miR-143 and miR-145 downregulation in tumor cells." (PMID 35205713, 2022). "Elevating SOX2 expression halted MB tumour growth and returning expression to endogenous levels allowed growth to resume in vitro." (PMID 36230692, 2022). "Inhibition of PCAT1/SOX2 in collaboration with radiation further inhibited tumour growth, and initiated the cGAS/STING signalling pathway, which enhanced the immune responses of radiotherapy in NSCLC." (PMID 35415876, 2022). "It has also been established as a driver for MB tumour recurrence, given that MBSCs expressing SOX2 are enriched following treatment." (PMID 36230692, 2022). "Immunohistochemical staining was used to detect the expression of RIP2, CD133, and SOX‐2 in xenograft tumor tissue." (PMID 36184801, 2022). "Our studies suggested the potential roles of PCAT1/SOX2 as predictors of tumour responses to the combination of radiation and immune checkpoint inhibitors." (PMID 35415876, 2022). "By giving tumor cells the ability to evade NK cells, SOX2 and SOX9 have been found to promote the immune evasion of tumor cells." (PMID 36524115, 2022). "Tissue microarrays of tumor samples for patients between 2007 and 2016 were used for immunodetection of Nestin, SOX2, SOX9, KLF4, NANOG, CD133 cMYC, and Ki67." (PMID 35795469, 2022). "For three of these tumor types, we have shown that SOX2 elevation in vivo induces a reversible state of tumor growth arrest, where tumor growth is abruptly halted when SOX2 is elevated until SOX2 returns to endogenous levels." (PMID 35454854, 2022). "Conditional deletion of Sox2 in murine skin reduced tumor formation following treatment with DMBA/TPA." (PMID 35892887, 2022). "The transcription factor SOX2 controls tumor initiation and T-ICs functions, and its expression is also regulated via AKT." (PMID 35236826, 2022). "Four main signaling pathways are involved in SOX2 expression favoring tumor maintenance: TGF-β, SHH pathway, EGFRvIII, RhoA-dependent pathway and focal adhesion kinase (FAK) signaling." (PMID 36232992, 2022). "Genes associated with self-renewal capacity, such as Nanog, Oct-4, and Sox-2, are overexpressed, thereby upregulating the expression of various types of cell-cycling genes and tumor initiation." (PMID 36359223, 2022).